SLC12A5 (solute carrier family 12 member 5)
Diseases named in the same sentence as SLC12A5 in open-access papers (continued):
Sharing a sentence is not in itself a finding about the gene and the disease.
glioma (continued). "By quantitative reverse transcriptase polymerase chain reaction, we detected that the expression of SLC12A5 gradually decreased with the increase of tumour grade and was higher in HA1800 than in other glioma cell lines." (PMID 38685685, 2024). "By regulating SLC12A5 expression, EZH2 activates the WNK1-OSR1-NKCC1 pathway, enhancing its interaction with ERM to promote glioma migration." (PMID 38886655, 2024). "While only two genes including SLC12A5 and KSR2 exhibited lower accessibility of enhancer region in GBM and decreased level of expression in glioma tissue." (PMID 38685685, 2024). "In this study, we discovered a potassium‐chloride co‐transporter SLC12A5 with altered genome architecture between HA1800 and A172, which is downregulated in high‐grade glioma and also as a protective factor contributed to outcome of patients." (PMID 38685685, 2024). "Bioinformatics analysis suggests that overexpression of SLC12A5 inhibits the proliferation of glioma U251MG cells, and SLC12A5 may be a novel effective biomarker of GBM with prognostic significance." (PMID 39061990, 2024). "Two predicted‐enhancer peaks of SLC12A5 in chromatin 20 were more open in LGG than GBM and its expression were also obviously decreased in glioma tissue indicating its tumour suppressor role in glioma." (PMID 38685685, 2024). "Therefore, we believe that EZH2 can regulate the expression of SLC12A5 to activate the WNK1-OSR1-NKCC1 cascade, which controls the migration of glioma cells." (PMID 38886655, 2024). "Among the genes in this model, solute carrier family 12, member 5 (SLC12A5) was considered as a neuron marker, but it has not been reported in glioma-related studies." (PMID 32296458, 2020). "Analysis of integrated glioma data from the TCGA database revealed a negative correlation between EZH2 and SLC12A5 expression." (PMID 38886655, 2024). "It has been proposed that glioma CSCs express differentiation markers similar to those in normal glia and neurons, such as of oligodendrocytes (ASCL1, OLIG2 and DLL3), astrocytes (GFAP), neurons (β-tubulin III, SYT1 and SLC12A5), and markers of inflamed astroglial cells (SERPINE1, TGFB1 and RELB)." (PMID 31661894, 2019).
autism (21 papers, 2015 to 2025). Persistent deficits in social interaction and communication and interaction as well as a markedly restricted repertoire of activity and interest as well as repetitive patterns of behavior. "Likewise, many neuronal genes with H3K27ac gain and increased expression under CHD2 deficient conditions are linked to the etiology of autism and other NDDs, including MYT1L, NRXN3, SLC12A5, and SNAP25 32–35." (PMID 36115870, 2022).
Seizure (14 papers, 2015 to 2025). A seizure is an intermittent abnormality of nervous system physiology characterized by a transient occurrence of signs and/or symptoms due to abnormal excessive or synchronous neuronal activity in the brain. "In this study, we identified four patients exhibiting severe infantile epileptic seizures with compound heterozygous mutations in SLC12A5, which encodes the neuronal K+-Cl− co-transporter KCC2." (PMID 27436767, 2016).
temporal lobe epilepsy (10 papers, 2012 to 2025). A localization-related (focal) form of epilepsy characterized by recurrent seizures that arise from foci within the temporal lobe, most commonly from its mesial aspect. "Consistent with their opposing roles in maintaining chloride homeostasis and GABA-shift, whereas NKCC1 protein levels were observed to be increased in patients with temporal lobe epilepsy (TLE), SLC12A5 (KCC2) mRNA expression was found to be downregulated." (PMID 35875665, 2022).
glioblastoma (7 papers, 2020 to 2025). The most malignant astrocytic tumor (WHO grade IV). "The different effects of VPA on PBT24 and SF8628 glioblastoma cells are associated with a higher impact of VPA on SLC12A5, which may be related to the more effective reduction of [Cl−]i level in PBT24 cells." (PMID 35625705, 2022). "It was reported that different VPA effect the expression of the SLC12A2 (NKCC1) and SLC12A5 (KCC2) co-transporter genes in pediatric glioblastoma PBT24 (boys) and SF8628 (girls) cells." (PMID 39061990, 2024). "The study aimed to determine the expression of carcinogenesis-related SLC5A8, SLC12A2, SLC12A5, CDH1, and CDH2 in adult glioblastoma U87 MG and T98G cells and the effects of 0.5 mM, 0.75 mM, and 1.5 mM doses of VPA." (PMID 39061990, 2024). "The expression of SLC12A2, SLC12A5, and CDH2 in adult glioblastoma U87 MG and T98G control cells differs significantly." (PMID 39061990, 2024). "High-grade glioblastoma cells are characterised by elevated levels of [Cl−]i, which is due to increased SLC12A2 and decreased SLC12A5 co-transporter activity." (PMID 36142368, 2022). "This study aimed to investigate the effect of 0.5 and 0.75 mM VPA on NKCC1 (SLC12A2), KCC2 (SLC12A5) and SLC5A8 (SLC5A8) co-transporter gene expressions in pediatric PBT24 (boy’s) and SF8628 (girl’s) glioblastoma cells." (PMID 35625705, 2022). "The different effects of VPA on the expression of SLC12A2, SLC12A5, and SLC5A8 in PBT24 and SF8628 glioblastoma cells suggest differences in tumor cell biology." (PMID 35625705, 2022). "Background/Objectives: The study aimed to determine the expression of carcinogenesis-related genes, such as SLC12A2, SLC12A5, CDH1, CDH2, EZH2, and GFAP, in primary glioblastoma (WHO Grade IV; IDH-wild-type) cells from three adult women: GBM5-1, GBM5-2F, and GBM5-3F." (PMID 41012498, 2025). "The distinct effects of VPA on the expression of SLC12A2, SLC12A5 and SLC5A8 in PBT24 and SF8628 glioblastoma cells suggest differences in tumor cell biology that may be gender-related." (PMID 35625705, 2022). "Glioblastoma cases belonging to the neural subtype were characterized by the expression of genes well-known as neuron markers such as GABRA1, neurofilament light chain (NEFL), synaptotagmin-1 (SYT1) and solute carrier family 12 member 5 (SLC12A5)." (PMID 33324155, 2020).
prostate carcinoma (6 papers, 2022 to 2025). A carcinoma that arises from epithelial cells of the prostate gland. "As SLC12A5 is associated with the neuroendocrine differentiation of prostate cancer while YTHDC1 regulates gene expression in an m6A-dependent manner." (PMID 36609444, 2023). "Taken together, these data suggested that SLC12A5 overexpression could lead to castration resistance and associate with neuroendocrine differentiation in prostate cancer." (PMID 36609444, 2023). "The oncogenic function for SLC12A5 has been reported in colorectal cancer, bladder urothelial carcinoma and prostate cancer that upregulation of SLC12A5 can promote tumour progression and increase cell invasion and metastasis ability in vivo and in vitro." (PMID 38685685, 2024). "A current study in prostate cancer proposed that the abnormal expression of SLC12A5, SLC25A17, and SLC27A6 were strong to metabolic reprogramming and the development of resistance against chemotherapeutic drugs." (PMID 38136890, 2023). "To probe the biological functions of SLC12A5 in prostate cancer, we first established SLC12A5-overexpressing stable cell lines by transfecting Flag-tagged SLC12A5 fusion vector into 22RV-1 and C4-2 cells." (PMID 36609444, 2023). "The enhanced expression of SLC12A5 mRNA was associated with neuroendocrine prostate cancer (NEPC) progression and poor survival in prostate cancer." (PMID 36609444, 2023). "Our co-immunoprecipitation and immunofluorescence cell staining assays confirmed that SLC12A5 directly bound to YTHDC1 in the nucleus of prostate cancer cells (the co-localization of SLC12A5 and YTHDC1 in the nucleus was also found in colorectal cancer cells)." (PMID 36609444, 2023). "Compared to the low-grade prostate cancer cell lines (LNCaP and C4-2), the SLC12A5 expression levels were remarkably higher in the high-grade prostate cancer cell lines (22RV-1, DU145 and PC3)." (PMID 36609444, 2023). "To further validate these results, we subsequently analyzed the TCGA prostate cancer datasets and found that the expression of SLC12A5 mRNA in prostate tumor tissues was significantly higher than that in normal tissues (P < 0.01)." (PMID 36609444, 2023). "SLC12A5 protein levels were significantly up-regulated in prostate cancer tissues compared with adjacent normal tissues (P < 0.01)." (PMID 36609444, 2023). "Immunofluorescence staining was then performed to clarify the localization of SLC12A5 protein in SLC12A5 highly expressed prostate cancer cell lines." (PMID 36609444, 2023). "Here we report that SLC12A5 functions as an oncogene to promote tumor progression and castration resistance of prostate cancer through the N6-methyladenosine (m6A) reader YTHDC1 and the transcription factor HOXB13." (PMID 36609444, 2023). "In conclusion, our study demonstrates SLC12A5 is gradually increased during the tumorigenesis and progression of prostate cancer." (PMID 36609444, 2023). "We have shown that the level of SLC12A5 was increased in prostate cancer, in comparison to its normal counterparts, and further elevated in castration-resistant prostate cancer (CRPC)." (PMID 36609444, 2023). "We compared the SLC12A5 protein levels in 49 paired tissues and confirmed that SLC12A5 protein levels were significantly enhanced in prostate cancer tissues compared with the matched adjacent normal tissues (P < 0.01)." (PMID 36609444, 2023). "In this study, we demonstrated that SLC12A5 functions as an oncogenic regulator as well in prostate cancer." (PMID 36609444, 2023). "Thus, HOXB13 is the target gene of SLC12A5/YTHDC1 complex in the nucleus that mediates the pro-tumor function of SLC12A5 in prostate cancer." (PMID 36609444, 2023). "Therefore, our findings reveal a mechanism that how the potassium-chloride cotransporter SLC12A5 promotes the tumor progression and provide a therapeutic opportunity for prostate cancer to apply the neurological disorder drug SLC12A5 inhibitors." (PMID 36609444, 2023).
prostate carcinoma (continued). "However, SLC12A5 was also found to be expressed in the nucleus of prostate cancer cell lines and tissues, which was in consistent with the previous observation in colorectal cancer." (PMID 36609444, 2023). "Our data reveal SLC12A5 could bind with YTHDC1 to form a SLC12A5-YTHDC1 complex to regulate prostate cancer specific transcription factor HOXB13 in an m6A-dependent manner, uncovering a novel mechanism about how SLC12A5 promotes tumor progression." (PMID 36609444, 2023). "Flag-SLC12A5 was able to bind with YTHDC1 in prostate cancer cells." (PMID 36609444, 2023). "SLC12A5 acts as a novel functional oncogene by promoting prostate cancer cell proliferation and migration, and conferring castration resistance and neuroendocrine differentiation in prostate cancer." (PMID 36609444, 2023). "Our study provides a possibility that drugs targeting SLC12A5 in neurological disorders may also be effective in prostate cancer." (PMID 36609444, 2023). "We selected 12 genes, which have been demonstrated to be required for the enzalutamide resistance and neuroendocrine differentiation of prostate cancer, and determined whether their expression are affected by the SLC12A5/YTHDC1 complex." (PMID 36609444, 2023). "Furthermore, we demonstrated that SLC12A5 promoted the castration resistance development of prostate cancer in addition to the cell proliferation and migration." (PMID 36609444, 2023). "Functionally, SLC12A5 increased the enzalutamide resistance in prostate cancer cells." (PMID 36609444, 2023). "We found that HOXB13 mRNA was up-regulated in SLC12A5-overexpressing 22RV-1 cells and this upregulation was partially abrogated by knocking down YTHDC1 in the SLC12A5-overexpressing 22RV-1 cells, suggesting that HOXB13 was the target gene of SLC12A5/YTHDC1 complex in prostate cancer." (PMID 36609444, 2023). "In the present study, we demonstrated YTHDC1 could mediate the tumorigenesis and castration resistance promoting role of SLC12A5 by forming a SLC12A5-YTHDC1 complex in prostate cancer." (PMID 36609444, 2023). "Next, we assessed whether the overexpression of SLC12A5 in prostate cancer contributed to its castration resistance development." (PMID 36609444, 2023). "We next determined whether YTHDC1 can mediate the SLC12A5’s oncogenic function in prostate cancer cells." (PMID 36609444, 2023). "Furthermore, we demonstrated that SLC12A5 can function as an oncogene to promote cell proliferation and migration, thus leading to the castration resistance and neuroendocrine differentiation of prostate cancer." (PMID 36609444, 2023). "Therefore, we first conducted a co-immunoprecipitation assay to verify whether SLC12A5 could interact with YTHDC1 in prostate cancer cells." (PMID 36609444, 2023). "YTHDC1 can form a complex with SLC12A5 to upregulate HOXB13, leading to the promotion of prostate cancer progression." (PMID 40221424, 2025). "We have demonstrated HOXB13 as a target gene of SLC12A5-YTHDC1 complex, supporting the oncogenic role of SLC12A5 in prostate cancer." (PMID 36609444, 2023). "Our data suggested that SLC12A5 was a novel player in the steps of CRPC progression and neuroendocrine differentiation in prostate cancer." (PMID 36609444, 2023). "Taken together, these results indicated that SLC12A5 interacted with YTHDC1 to form a SLC12A5-YTHDC1 complex in the cell nucleus, thus mediated the progression of prostate cancer." (PMID 36609444, 2023). "In this study, we have shown that SLC12A5 increased over the prostate cancer progression and was positively correlated with higher Gleason score, advanced TNM stage, and poor survivals in prostate cancer patients." (PMID 36609444, 2023). "Mechanistically, SLC12A5 interacts with the m6A reader YTHDC1 in the nucleus and in turn upregulates the transcription factor HOXB13 to promote the tumor progression of prostate cancer." (PMID 36609444, 2023).
prostate carcinoma (continued). "Interestingly, SLC12A5 was detected in the cell nucleus and formed a complex with nuclear m6A reader YTHDC1, which in turn upregulated HOXB13 to promote the prostate cancer progression." (PMID 36609444, 2023). "Moreover, SLC12A5 expression levels were analyzed by qRT-PCR in five prostate cancer cell lines (LNCaP, C4-2, 22RV-1, DU145 and PC3) that represent different stages of prostate cancer." (PMID 36609444, 2023). "The expression levels of SLC12A5 were also positively correlated with higher Gleason score, advanced TNM stage (large tumor size, lymph node spread, distant metastases) and higher PSA levels in TCGA dataset, suggesting a potential oncogenic role of SLC12A5 in prostate cancer progression." (PMID 36609444, 2023).
bladder cancer (4 papers, 2017 to 2024). "For example, SLC12A5 can interact with and enhance SOX18 activity to promote bladder cancer progression via the NF‐κB/MMP‐7 pathway." (PMID 36645171, 2023).
colorectal cancer (4 papers, 2022 to 2024). A primary or metastatic malignant neoplasm that affects the colon or rectum. "SLC12A5 gene was found to be amplified in colorectal cancer by single cell sequencing and this amplification contributed to tumor progression and metastasis of colorectal cancer." (PMID 36609444, 2023). "Furthermore, SLC12A5 was shown to significantly promote the G1/S cell cycle transition and enhance lung metastasis in colorectal cancer." (PMID 39507532, 2024). "The overexpression of SLC12A5 significantly increased the proliferation and colony formation of both 22RV-1 and C4-2 cell lines (P < 0.01), in consistent with the previous observation in colorectal cancer (Ref." (PMID 36609444, 2023). "Surprisingly, we found that SLC12A5 protein was expressed not only in the cell membrane, but also in the nucleus in 22RV-1, PC3 and DU145 cells, which is consistent with the observation in colorectal cancer cells (Ref." (PMID 36609444, 2023). "In the other hand, knocking down SLC12A5 in DU145 and PC3 cells by small interfering RNAs (siRNAs) significantly decreased cell proliferation and cell migration, corroborating with the findings in colorectal cancer (Ref." (PMID 36609444, 2023). "To further determine whether the interaction between endogenous SLC12A5 and YTHDC1 occurs in the cell nucleus, we conducted an immunofluorescence staining and found that endogenous SLC12A5 co-localized with YTHDC1 in the cell nucleus in SLC12A5 high-expressing prostate and colorectal cancer cells." (PMID 36609444, 2023).
Obesity (4 papers, 2019 to 2025). Accumulation of substantial excess body fat. "By contrast, the prevalence of obesity among female carriers of PTV variants in DIDO1 and SLC12A5 was more than 80%, albeit there were relatively fewer carriers (12 of 14 and 9 of 11 carriers were obese, respectively) (PHeterogeneity = 9.9 × 10−6 and PHeterogeneity = 2.6 × 10−4, respectively)." (PMID 37601970, 2023).
bladder urothelial carcinoma (3 papers, 2017 to 2024). "SLC12A5 is a type of Kcl cotransporter that maintains neuronal chloride homeostasis, and its aberrant expression is involved in tumorigenesis in various cancer types, such as bladder urothelial carcinoma and colon cancer." (PMID 34660294, 2021). "However, the clinical significance and biological role of SLC12A5 in human bladder urothelial carcinoma (BUC) remains unclear." (PMID 28333147, 2017).
colon cancer (3 papers, 2017 to 2022). "Activation of SLC12A5 becomed a potential oncogenic driver event in colon cancer by promoting cell proliferation and inhibiting. apoptosis." (PMID 35785171, 2022).
epilepsy syndrome (3 papers, 2019 to 2024). A syndrome that has a characteristic cluster of clinical features and/or lectroencephalographic (EEG) findings that reflect underlying epileptic activity. "Overall, familial cases in this cohort were more likely to exhibit variants in genes associated with established epilepsy syndromes, such as ASH1L, SLC12A5, and DEPDC5." (PMID 39767570, 2024).
Hypertension (3 papers, 2015 to 2025). The presence of chronic increased pressure in the systemic arterial system. "At the genetic level, our independent differential and prognostic analyses identified FOXD3, F10, and SLC12A5 as genes shared between thyroid cancer and hypertension." (PMID 40785195, 2025). "Moreover, our findings underscore the critical role of differentially expressed genes, particularly FOXD3, F10, and SLC12A5, in the pathogenesis of both hypertension and thyroid cancer." (PMID 40785195, 2025).
Intellectual disability (3 papers, 2021 to 2024). "Here, the functionality and expression of the novel SLC12A5 missense variant R231H we discovered in a patient diagnosed with EIMFS and profound intellectual disability were assessed in vitro by gramicidin-perforated patch-clamp, NH4+ assay and surface immunolabeling." (PMID 38660387, 2024). "In GMCK-RD, a number of novel genes have been identified, resulting in improved biological understanding of disease mechanisms and better patient care as exemplified by KAT6A (intellectual disability), SLC12A5 (epilepsy of infancy), and MIR140 (skeletal dysplasia)." (PMID 33726816, 2021).
lung adenocarcinoma (3 papers, 2019 to 2021). A carcinoma that arises from the lung and is characterized by the presence of malignant glandular epithelial cells. "In this study, we constructed a mRNA-mRNA related ceRNET of lung adenocarcinoma (LUAD) and identified the highlighted TWIST1-centered ceRNET, which recruits SLC12A5 and ZFHX4 as its ceRNAs." (PMID 31645542, 2019).